RB1 (RB transcriptional corepressor 1)
Diseases named in the same sentence as RB1 in open-access papers (continued):
Sharing a sentence is not in itself a finding about the gene and the disease.
tumor (continued). "In two of the tumors the RB1 gene was inactivated by two small mutations and in the third tumor RB1 was inactivated by a chromosomal loss, which is the second most frequent type of mutation." (PMID 29261756, 2017). "One of the four MYCN‐amplified, high‐risk tumors, (UPENN‐RB‐175) was RB1+/+ and was diagnosed at 10 months, by which time the tumor had invaded both the retrolaminar portion of the optic nerve and showed massive choroidal invasion." (PMID 28211617, 2017). "The extremely high mutation frequency of cdkn2a/b or rb1 in tumor tissues derived by TALENs injection also supports the possibility of tumor induction by specific inactivation of cdkn2a/b or rb1." (PMID 28903419, 2017). "Mutation forms of rb1 in tumor tissues of rb1 TALEN-injected F0 tp53e7/e7 mutant zebrafish were analyzed." (PMID 28903419, 2017). "The RB1 tumor suppressor gene encodes for the pRb protein that regulates transcription of cell cycle genes." (PMID 29124525, 2017). "The genetic alterations following RB1 loss is highly variable and this heterogeneity affect tumor progression and patient outcome." (PMID 29124525, 2017). "This tumor is caused due to inactivation of both the alleles of Retinoblastoma (RB1) gene resulting in the defective pRB protein." (PMID 29162051, 2017). "Overexpression of RB1, the first identified tumor suppressor, causes cells to undergo arrest in the G1 phase of the cell cycle, and, as expected, abrogation of RB1 accelerates G1 transition." (PMID 29225781, 2017). "Decreased survival in patients with wt RB1 was associated with significantly increased chemo-refractory tumor response relative to patients harboring mutant RB1 tumors (p = 0.0364)." (PMID 29088741, 2017). "In this study, we developed somatically mutated tumor models using TALEN-mediated somatic gene inactivation of cdkn2a/b or rb1 tumor suppressor genes in zebrafish." (PMID 28903419, 2017). "Retinoblastoma (Rb), the most common pediatric intraocular neoplasm, results from inactivation of both alleles of the RB1 tumor suppressor gene." (PMID 26925970, 2016). "In OS, degree of tumor differentiation, which holds powerful prognostic significance, demonstrates an inverse correlation with RB1 loss." (PMID 29263893, 2016). "This task is compounded by the fact that most of the tumor-derived mutant alleles of RB1 that have been characterized to date have extensive effects on protein structure or stability and are little use for separating activities." (PMID 27401552, 2016). "One would therefore predict that loss of SWI/SNF complex activity, and more specifically the loss of BRG1 expression, would abrogate the ability of RB1 to inhibit growth and thereby block the general ability of TKIs to halt tumor growth." (PMID 28105458, 2016). "The RB pathway was considered disrupted in a tumor if one of the following events occurred: 1) RB1 mutation/homozygous deletion/underexpression; 2) CDKN2A mutation/homozygous deletion/underexpression; or 3) CCND1 overexpression." (PMID 27832204, 2016). "Real time PCR revealed largely reduced presence of the RB1 gene in both tumors suggesting that at least the majority of tumor cells had lost both RB1 alleles." (PMID 27121059, 2016). "In a few cases, mutant alleles of binding partners have been shown to modify the tumor phenotype associated with mutant RB1 alleles." (PMID 27401552, 2016). "The retinoblastoma susceptibility gene (RB1) was the first tumor suppressor gene to be molecularly defined." (PMID 27401552, 2016). "This study aimed to identify recurrent genetic alterations subsequent to RB1 loss that drive tumor progression." (PMID 27126562, 2016). "Conversely, tumours with complete RB1 loss have hard-wired activation of cyclin/CDK-mediated cell proliferation." (PMID 25896606, 2015). "With EBV, RB1 methylation was a tumor-associated event because only the cancer group presented methylated RB1 with HPV infection." (PMID 26032781, 2015).
tumor (continued). "The first aims to exploit RB1 loss for therapeutic purposes, whereas the second is intended to reactivate RB1 tumor suppressor function." (PMID 26160835, 2015). "Despite distinct histologies and cell contexts of source tumours, RB1 loss-of-function mutations and NFE2L2 mutations/amplifications exhibited similar expression patterns." (PMID 26436532, 2015). "Loss of heterozygosity (LOH) was found in 65% of the tumors, which is consistent with previous reports suggesting that loss of RB1 allele plays an important role in tumor development." (PMID 25602518, 2015). "Accordingly, we observed that RB1 mutations correlated with E2F family gene upregulation across tumour types." (PMID 26436532, 2015). "E2F1 promotes cellular proliferation pathways as loss of E2F1 inhibits tumor development in tumor prone mice heterozygous for RB1." (PMID 26670255, 2015). "Together, the data indicate that biallelic inactivation of rb1 in somatic tissue underlies neoplastic transformation and tumor initiation." (PMID 26345384, 2015). "Rb1 functional pathway abnormalities have been reported to lead to P16 over-expression in dysplastic and neoplastic tissue e.g. in tumors of the lower genital tract due to high-risk types of human papillomavirus which lead to inactivation of Rb1." (PMID 26043844, 2015). "Twenty inactivating mutations (PTC and splicing mutations) were also identified in tumor suppressor genes including RB1 (n = 1), NF1 (n = 3) or MLH1 (n = 2)." (PMID 26155992, 2015). "Ras pathway mutations are detected by the Rb1 tumor suppression pathway, and mutation or inactivation of the Rb1 pathway is required for EMT." (PMID 25880398, 2015). "The general features of tumor distribution were apparent in patients with both germline and somatic RB1 mutations when analyzed in separate subsets." (PMID 26230335, 2015). "PTEN M264I mutation was identified only in a TKI-refractory lesion with SCLC transformation, while PIK3CA and RB1 mutations were identified only in pre-treatment primary tumour samples." (PMID 26400668, 2015). "Because a common oncogenic defect in basal-a/TNBC tumor cells is the loss of the retinoblastoma tumor suppressor (Rb1), a cytostatic CDK4/6 drugs that target Rb1 function was investigated as a mechanism to enhance the therapeutic window for Mps1 inhibition." (PMID 26398286, 2015). "With EBV, the methylation of RB1 was a tumor-associated event, where only the cancer group presented RB1 methylation in the presence of this virus." (PMID 26032781, 2015). "We have shown in this study that in combination with exogenous genomic stress like ionizing radiation these low penetrance variations in RB1 can significantly alter the tumor susceptibility of an organism." (PMID 25092376, 2014). "In the present study we combined mapping of tumor-specific allele-losses across the susceptibility locus with positional-candidate mapping and identified a functional gene polymorphism in Rb1." (PMID 25092376, 2014). "This is the first experimental demonstration of a functional and genetic link between reduced Rb1 expression from a common promoter variant and increased tumor risk after radiation exposure." (PMID 25092376, 2014). "NGS of a tumor sample obtained from a lung resection performed at the time of the first recurrence after the initial liver transplantation revealed RB1 loss." (PMID 24931142, 2014).
tumor (continued). "NGS performed on a tumor sample from the liver biopsy obtained at the time of diagnosis revealed RB1 loss." (PMID 24931142, 2014). "This tumor had high allele fraction mutations in RB1 exclusively in two other regions (D and E) within the same tumor." (PMID 25608559, 2014). "Two of the genes initially classified as following the first pattern (PTEN and RB1) showed a statistically significant increase in the proportion of nonsense mutations in cell lines in comparison to tumor samples." (PMID 25119593, 2014). "We further evaluated the impact of PNS, Rg1, Rb1 or R1 on the angiogenic events and associated miR expression in tumor and heart in this complex model." (PMID 24903055, 2014). "The primary aim of this study was to determine the role of Rb1 loss in tumor initiation and progression using conditional genetic mouse models of aRMS." (PMID 24274149, 2013). "Patients with identified de novo mutations in both alleles of RB1 in the tumor and at least one wild type RB1 allele from peripheral blood mononuclear cell DNA (representing the germline genotype) were selected for study." (PMID 23826078, 2013). "Several studies in mice and cultured cells have linked RB1 inactivation to defects in chromosome segregation that can contribute to tumor cell aneuploidy and CIN." (PMID 23765217, 2013). "Surprisingly we find that eRapa treatment has a dramatic and positive effect on life span in both sexes of Rb1+/− mice, which is associated with slower tumor development and growth." (PMID 23454836, 2013). "As for genomic loss, 9p21.3 (CDKN2A), 9p23-p24.1 (PTPRD) and 13q14.2 (RB1) were significantly less frequently deleted in ALK fusion-positive tumours." (PMID 23289484, 2013). "Patient 2 developed a large deletion in the RB1 gene and then, by nondisjunction and reduplication of the 13th chromosome in a tumor-initiating cell, became homozygous for the mutated RB1 gene." (PMID 23826078, 2013). "Recent studies indicate that in addition to RB1 gene mutation, tumor development also involves promoter DNA methylation of other tumor suppressor genes." (PMID 23559860, 2013). "Patient 4 developed a mutation in a retinal cell, and subsequent epigenetic silencing by methylation of the remaining normal RB1 allele resulted in the tumor-initiating cell." (PMID 23826078, 2013). "Patient 3 had an RB1 mutation in the germ line and subsequently developed a second unique mutation in the tumor-initiating cell." (PMID 23826078, 2013). "Accordingly, in those tissues with very low p107 and p130 expression levels, pRb compensation is unlikely, making those tissues more susceptible to tumor development as a consequence of Rb1 loss." (PMID 24381932, 2013). "We investigated the complementary role of Rb1 loss in aRMS tumor initiation and progression using conditional mouse models." (PMID 24274149, 2013). "RB1 loss has long been recognized as the causative genetic alteration underlying RB but it is increasingly evident that other genetic and epigenetic alterations are also required for the tumor to develop." (PMID 23233862, 2012). "The authors also showed that homozygous inactivation of P2RY5 was antecedent to the loss of RB1 during tumor development, and that nucleotide substitutions in P2RY5 increased cancer risk." (PMID 23233862, 2012). "A comprehensive review by Burkhart and Sage of cellular mechanisms of tumor suppression by the retinoblastoma gene discusses the loss of RB1 function and cancer progression." (PMID 23036192, 2012). "Our previous experiments have indicated that compound heterozygous loss of both Men1 and Rb1 genes has little effect on the rate, severity or onset of tumorigenesis, or on the spectrum of observed tumour types compared to individual gene deletions." (PMID 22708734, 2012).
tumor (continued). "Either type of alteration is associated with inactivation of RB1 expression in about 50% of tumours." (PMID 22685381, 2012). "LOH or deletion of the RB1 locus has been detected in 19–67% of tumours, and RB1 mutations have been detected in about 25–35% of cases." (PMID 22685381, 2012). "Mutation affecting regulatory sequences in the RB1 promoter also reduce the expression of normal Rb protein below a certain threshold level necessary for tumor suppression function." (PMID 21615945, 2011). "Conventionally, the protein expression level of RB1 as measured by immunohistochemistry (IHC) has been used to estimate the prevalence of RB1 deficiency in various tumor types." (PMID 21447152, 2011). "The prevalence of RB1 deficiency in clinical tumor and normal samples were also consistent with previous reports using IHC for RB1." (PMID 21447152, 2011). "Recent studies in primary cells and tumor cell lines have shown that decreased expression of RB1 causes decreased NCAP-D3 levels, which resulted in a more disorganized metaphase plate and chromosome missegregation." (PMID 21464947, 2011). "In all tumor groups, we found a recurrent region of loss on chromosome 13q (mouse chromosome 14) which is commonly associated with the RB1 gene." (PMID 20735817, 2010). "To assess the frequency of similar mutations in the RB1 gene in human cancer, we screened blood and tumor samples for similar alleles." (PMID 20298605, 2010). "In this study, we identify and characterize a tumor derived allele of the retinoblastoma gene (RB1) that possesses a discrete defect in its ability to interact with LXCXE motif containing proteins that compromises proliferative control." (PMID 20298605, 2010). "High p16INK4a staining (3+), which is a hallmark of lost RB1 function, was seen in 32 of 119 tumours assayed and often included both nuclear and cytoplasmic staining." (PMID 18782450, 2008). "The tumor-suppressor gene RB1 can suppress S phase entry and cause a transient G1 arrest following DNA damage and the mutations in Rb1 pathway-related genes are associated with poor prognosis in many tumor types." (PMID 18800172, 2008). "In basal-like tumours in vivo, however, the exact opposite seems to occur in that the RB-pathway barrier appears to be RB1 functional loss with a concomitant feedback loop that induces p16INK4a gene and protein expression." (PMID 18782450, 2008). "The differential effect of RB1 loss on p16INK4a expression in luminal B versus basal-like tumour cells implicates other transcription factors in addition to pRb-E2F in the regulation of this CDK inhibitor in luminal tumours." (PMID 18782450, 2008). "When considered together, these data suggest that RB1 LOH in basal-like tumours cause a loss of RB1 protein function, which the cells attempt to compensate for by increasing p16INK4a gene and protein expression levels." (PMID 18782450, 2008). "In total, these data strongly argue that the RB-pathway lesion that occurs in most basal-like tumours is RB1 loss, possibly with a compensatory activation of p16INK4a." (PMID 18782450, 2008). "Although the RB-1 gene was first identified through its role in a rare pediatric cancer, subsequent tumor studies have shown that this gene is sporadically mutated in a wide range of cancers." (PMID 18834508, 2008). "p16INK4a was highly expressed in basal-like tumours, presumably due to a previously reported feedback loop caused by RB1 loss." (PMID 18782450, 2008). "Additional support for the functional loss of RB1 in basal-like tumours comes from the correlation with high p16INK4a message and protein expression." (PMID 18782450, 2008). "Many other examples of mutations of tumour suppressors are evident in cancer and include RB1, APC, PTEN, P21 and others." (PMID 19506729, 2008).
tumor (continued). "RB1 loss of heterozygosity was observed at an overall frequency of 39%, with a high frequency in basal-like (72%) and luminal B (62%) tumours." (PMID 18782450, 2008). "p16INK4a is also highly expressed both by microarray and by immunohistochemistry in most of the RB1 LOH basal-like tumours, presumably due to a feedback caused by RB1 loss." (PMID 18782450, 2008). "Perhaps the reason why a vast majority of tumor-derived alleles of RB-1 eliminate the pocket domain completely is because they represent the easiest way to disrupt everything that pRB does." (PMID 17854503, 2007). "The retinoblastoma susceptibility gene (RB1) encodes a nuclear phosphoprotein RB with tumor suppression function." (PMID 17183714, 2006). "The overall frequency of recurrent losses was lower, with no region lost in more than 50% of tumors; the most frequently lost tumor suppressor gene was RB1 (hemizygous loss in 26% of tumors)." (PMID 16457699, 2005). "Loss of RB1 expression is associated with a higher grade of malignancy and appears to be a prognostic factor in several human neoplasms." (PMID 12556968, 2003). "These authors also demonstrated that the majority of GB with loss of RB1 expression had RB1 promoter hypermethylation, whereas the majority of tumours with RB1 expression had normal RB1 gene status." (PMID 12556968, 2003). "Loss of RB1 function has been described in a variety of tumour types, and significant association has been observed between loss of heterozygosity (LOH) of RB1 intragenic markers and the absence of pRB expression." (PMID 12556968, 2003). "We found no alterations at the essential promoter region, and only two tumours (diagnosed as GB and O) displayed sequence anomalies at the protein-binding pocket domain (exons 20–24) we screened by SSCP; both tumours retained two RB1 alleles." (PMID 12556968, 2003). "In the sporadic unilateral Rb tumours, both RB1 mutations are required in the same somatic cell to initiate tumour formation." (PMID 12232763, 2002). "In an analysis of mutations in the RB1 gene in three patients, selected at random, who had a positive family history of tumours, we identified mutations, in constitutional cells, involving exons 3, 13 and 17 of the RB1 gene." (PMID 8217609, 1993). "Nevertheless, whether other retinal cell types can drive RB1-deficient tumor development remains unclear." (PMID 41535675, 2026). "Risk factors for PB include germline mutations in two tumor suppressors, RB1 and DICER1." (PMID 40075567, 2025). "In summary of the analysis of the primary tumour vs. LNM, the evaluation of the mutation classified as reliably pathogenic (RET gene (chr10:43609933, c.1886_1891delTGTGCG; RB1 gene, chr13:49033890, c.2039T>C) shows a match between primary tumour tissue and LNM." (PMID 40729029, 2025). "This leads to biallelic loss of RB1, disrupting cell cycle control and enabling tumor development." (PMID 41009976, 2025). "The loss of RB1 impairs cell cycle regulation, hence increasing tumor aggressiveness." (PMID 40342734, 2025). "The combined use of NGS-based liquid biopsy on cfDNA from AH and plasma, together with LR-WGS, proved effective in simultaneously detecting somatic RB1 inactivation (“two-hit” pattern), germline susceptibility linked to the 13q duplication, and tumor clonal evolution involving CNVs and SNVs." (PMID 41465072, 2025).